SNHG11 (small nucleolar RNA host gene 11)
Synonyms: LINC00101; C20orf198; NCRNA00101
Gene: Long non-coding RNA gene on chromosome 20 (38,446,343 to 38,450,943, forward strand). Ensembl gene ENSG00000174365.
Gene Ontology:
Biological process: RNA processing
Cellular component: nucleolus
Diseases named in the same sentence as SNHG11 in open-access papers:
SNHG11 is named in the same sentence as 26 diseases in open-access papers, as found by Europe PMC text mining. Sharing a sentence is not in itself a finding about the gene and the disease. The quoted sentences say what the papers report.
colorectal cancer (10 papers, 2020 to 2025). A primary or metastatic malignant neoplasm that affects the colon or rectum. "Small nucleolar RNA host gene 11 (SNHG11) is a lncRNA that has been found to be upregulated in bevacizumab-resistant colorectal cancer." (PMID 40781643, 2025). "High SNHG11 expression promotes proliferation and metastasis in colorectal cancer (CRC) by targeting the hippo pathway." (PMID 35574307, 2022). "Besides, SNHG11 was shown to be upregulated in colorectal cancer and blocked the interaction between pVHL and HIF-1α via binding to HIF-1α, preventing HIF-1α ubiquitination and degradation." (PMID 34699314, 2021). "SNHG11 was a member of a small nucleolar RNA host gene family involved in various tumor progressions, such as promoting proliferation and metastasis by targeting the Wnt/β‐catenin signaling pathway and the Hippo pathway in lung cancer and colorectal cancer, respectively." (PMID 33232580, 2020). "SNHG11 binds to the HRE site in the gene promoter, and promotes gene transcription and tumor invasion and metastasis of colorectal cancer through the SNHG11/HIF-1α pathway." (PMID 35597996, 2022). "Overexpression of PART1, SNHG11, LINC00173 and MIR17HG is widely involved in tumorigenesis and malignant progression of several types of cancer, such as glioma, breast cancer, lung cancer and colorectal cancer." (PMID 34243770, 2021).
hepatocellular carcinoma (4 papers, 2021 to 2024). A malignant tumor that arises from hepatocytes. "In contrast, miR-184 was stated to be regulated by SNHG11, which belongs to long non-coding RNAs (lncRNAs); thus, its decrease resulted in decreased cellular proliferation, migration, and enhanced apoptosis in hepatocellular carcinoma (HCC)." (PMID 39594634, 2024). "LncRNA SNHG11 (also known as small nucleolar RNA host gene 11) is found to facilitate cell proliferation and migration in a variety of cancers, such as lung cancer, glioma, and hepatocellular carcinoma (HCC)." (PMID 35574307, 2022). "Of note, the promoting effect of H19 and SNHG11 on EMT have been validated in gastric cancer, hepatocellular cancer, and glioma." (PMID 34880375, 2021).
lung carcinoma (4 papers, 2020 to 2025). "For example, SNHG11, which is upregulated in lung cancer and correlates with poor prognosis, promotes tumor progression by activating the Wnt/β-catenin pathway through two distinct mechanisms: acting as a ceRNA via the SNHG11/miR-4436a/CTNNB1 axis and by directly binding to β-catenin." (PMID 41301542, 2025).
gastric cancer (3 papers, 2021 to 2024). A primary or metastatic malignant neoplasm involving the stomach. "The aim of this study was to assess the regulatory functions of SNHG11 in gastric cancer (GC) cell proliferation and migration." (PMID 33816469, 2021).
Hyperglycemia (2 papers, 2024 to 2026). An increased concentration of glucose in the blood. "Similarly, mmu_circ‐Snhg11, which was downregulated under hyperglycemia, was restored by hypoxic exosome treatment." (PMID 41508422, 2026). "Through the participation of the miR-144–3p/HIF-1 axis, circ-Snhg11 overexpression exosome from ADMSCs may suppress hyperglycemia-induced endothelial cell damage and drive the polarization of macrophages towards M2 phenotype." (PMID 38632264, 2024). "Under hyperglycemia conditions, circ-Snhg11 expression decreased." (PMID 38632264, 2024).
Obesity (2 papers, 2019 to 2023). Accumulation of substantial excess body fat. "SNHG11 (small nucleolar RNA host gene 11) is an obesity-associated lncRNA, and is involved in positive regulation of cell proliferation in OC." (PMID 31182053, 2019).
prostate carcinoma (2 papers, 2022 to 2024). A carcinoma that arises from epithelial cells of the prostate gland. "Overexpression of lncRNAs PlncRNA-1 and SNHG11 in prostate cancer is also critical for cell proliferation and metastasis." (PMID 38249783, 2024). "Notably, SNHG11 boosts IGF-1R expression and recruits miR-184, leading to increased prostate cancer cell proliferation, invasion, and migration." (PMID 38249783, 2024).
acute pancreatitis (1 paper, 2022). An acute inflammatory process that leads to necrosis of the pancreatic parenchyma. "More importantly, our conclusions indicate that SNHG11 and PLCB1 genes may not only be involved in acute pancreatitis and also be one of the important targets of other inflammations in the body, which deserves more exploration on the role of SNHG11 and PLCB1 genes in the disease in the future." (PMID 36611865, 2022).
breast invasive carcinoma (1 paper, 2020). "In addition, SNHG11-correlated genes in rectum adenocarcinoma, prostate adenocarcinoma, kidney renal papillary cell carcinoma, kidney renal clear cell carcinoma, and breast invasive carcinoma were also enriched in the HIF-1 signaling pathway." (PMID 33060856, 2020).
glioblastoma (1 paper, 2021). The most malignant astrocytic tumor (WHO grade IV). "SNHG11 was confirmed to express highly in glioblastoma compared to normal brain, and it could promote proliferation, migration, and invasion via epithelial–mesenchymal transition by sponging miR154-5p." (PMID 34194477, 2021).
Intellectual disability (1 paper, 2023). "Our study uncovers the functional role of Snhg11 in the DG and underscores the significance of this lncRNA in intellectual disability." (PMID 37841843, 2023).
lung adenocarcinoma (1 paper, 2025). A carcinoma that arises from the lung and is characterized by the presence of malignant glandular epithelial cells. "Likewise, lncRNA Small Nucleolar RNA Host Gene 11 (SNHG11) enhanced NOTCH3 expression sponging miR-193a-5p, thereby activating the NOTCH signaling pathway and facilitating the progression of lung adenocarcinoma." (PMID 40563292, 2025).
mesothelioma (1 paper, 2025). A usually malignant and aggressive neoplasm of the mesothelium which is often associated with exposure to asbestos. "Additionally, we identified other lncRNAs enriched in PM-EVs, such as SNHG9, SNHG11 and SNHG15, which have been previously associated with cancer development and were associated with mesothelioma patients’ survival in our analysis." (PMID 39920655, 2025).
myocardial infarction (1 paper, 2024). Gross necrosis of the myocardium, as a result of interruption of the blood supply to the area, as in coronary thrombosis. "In addition to protein-coding genes, three long non-coding RNA genes were also differentially edited, including myocardial infarction-associated transcript (Miat), small nucleolar RNA host gene 11 (Snhg11) and maternally expressed gene 3 (Meg3)." (PMID 39135964, 2024).
pancreatic cancer (1 paper, 2024). "Moreover, the exosomal small nucleolar RNA host gene 11 (SNHG11) promoted cell proliferation, migration, and angiogenesis in pancreatic cancer cell lines but impeded cell apoptosis via sponging miR-324-3p to upregulate VEGFA expression." (PMID 38392967, 2024).
pancreatitis (1 paper, 2022). Inflammation of the pancreas. "SNHG11 has been linked to the occurrence and development of various tumors, but its mechanism and role in the progression of pancreatitis are still unclear." (PMID 36611865, 2022). "Our results show that the apoptosis-delaying effect of SNHG11 in pancreatitis cell models is restored after miR-7-5p overexpression, and more importantly, SNHG11-induced inflammation in pancreatitis cell models factor alterations are also reverted by miR-7-5p." (PMID 36611865, 2022). "Our results show that when SNHG11 is overexpressed in the rat AP model (injection of SNHG11 adenovirus), the progression of pancreatitis can be weakened." (PMID 36611865, 2022). "Subsequently, in the in vitro experiments, the AR42J and HPDE6-C7 pancreatitis models induced by caerulein confirmed that overexpression of SNHG11 can reduce the expression of inflammatory factors IL6, IL1-β, and TNF-alfa." (PMID 36611865, 2022). "Following that, we hoped to delve deeper into the potential mechanism by which SNHG11 influences pancreatitis progression." (PMID 36611865, 2022). "This is the first time SNHG11 has been shown to play a role in pancreatitis." (PMID 36611865, 2022). "Our results demonstrated decreased SNHG11 in both rat and cellular pancreatitis models." (PMID 36611865, 2022). "To further explore whether SNHG11 exerts its effect on miR-7-5p, we performed four interventions in pancreatitis cell models, namely empty+mimics-NC, SNHG11+mimics-NC, empty+mimics-miR-7-5p, SNHG11+mimics-miR-7-5p, and verified the differential change of miR-7-5p between them." (PMID 36611865, 2022). "Therefore, this study explored the potential mechanism of SNHG11’s role in pancreatitis." (PMID 36611865, 2022). "In our study, we discovered the relationship between the new target molecules SNHG11 and PLCB1 genes and inflammatory cytokines in pancreatitis and confirmed the regulation of SNHG11 and PLCB1 genes on inflammatory cytokines in vitro in vivo experiments." (PMID 36611865, 2022).
tumor (14 papers, 2019 to 2025). "The examination of molecular mechanisms of SNHG11 in CRC pathogenesis showed that SNHG11 mRNA expression was higher in CRC cell lines derived from primary tumor compared to cell lines derived from CRC metastases." (PMID 38226210, 2024). "In summary, these results identify a SNHG11/ HIF-1α axis that plays a pivotal role in tumor invasion and metastasis." (PMID 33060856, 2020). "The in vivo assays also indicated that SNHG11 knockdown inhibited tumor growth in CRC mice models." (PMID 38226210, 2024). "SNHG11, a small nucleolar RNA (snoRNA) host gene, is a well-recognized cancer-promoting lncRNA and promotes autophagy, proliferation, migration, and invasion of multiple tumor cells." (PMID 34880375, 2021). "For example, tumor-killing immune cells in the high expression group of SNHG16, SNHG6, SNHG11, FAM222A-AS1, RHPN1-AS1, SNHG1, and SNHG7 were significantly lower than those in the low." (PMID 35646635, 2022). "In the top 10 altered couples for these tumor types, 9 are identical: SNORA13/EBP41L4A-AS1, SNORA27/RPL21, SNORA31/TPT1, SNORA71E/SNHG11, SNORA72/RPL30, SNORD102/RPL21, SNORD12/ZFAS1, SNORD12B/ZFAS1, and SNORD12C/ZFAS1." (PMID 32046192, 2020). "For instance, SNORA71E/SNHG11 is in the top 10 of over-expressed targets in all tumor types, SNORA72/RPL30 is in the top 10 for all tumor types but KIRCs and OVs, and SNORA5C/TBRG4 is only missing in UCECs, OVs, and GBMs shortlists." (PMID 32046192, 2020). "The low expression group of SNHG16, SNHG6, SNHG11, FAM222A-AS1, RHPN1-AS1, SNHG1, and SNHG7 was accompanied by more immune cell infiltration, further supporting that PANoptosis plays a crucial role in the tumor immune microenvironment." (PMID 35646635, 2022). "In addition, the combination of several tumor markers, such as lncRNA ZFAS1, SNHG11, LINC00909, and LINC00654, can improve the accuracy of CRC diagnosis." (PMID 34778084, 2021).
cancer (10 papers, 2019 to 2025). A tumor composed of atypical neoplastic, often pleomorphic cells that invade other tissues. "The top marker gene for Cluster 7 was Snhg11, a long non-coding RNA (lncRNA) primarily implicated in cancer cell progression." (PMID 36544903, 2022). "In HCC, SNHG11 regulated proliferation, migration, apoptosis, and autophagy of cancer cells through a hsa‐miR‐184/AGO2 axis." (PMID 33232580, 2020). "The five prognostic genes have all been reported to be associated with human cancer, and three (GAS5, HCP5, and SNHG11) have reported associations with OC." (PMID 31182053, 2019). "Since hypoxia is a common feature of many solid tumors, we explored whether the HIF-1α/SNHG11 axis functions in other cancers." (PMID 33060856, 2020). "Interestingly, Snhg11 has been shown to promote cancer progression via activation of Wnt signaling." (PMID 36544903, 2022). "Interestingly, TCGA data revealed that SNHG11 was upregulated in cancers other than CRC." (PMID 33060856, 2020). "Even though the relevance of these two snoRNAs has not yet been reported, different groups have reported alterations in SNHG11 and TBRG4 in different cancer types." (PMID 32046192, 2020).
infection (1 paper, 2025). The state of being infected such as from the introduction of a foreign agent such as serum, vaccine, antigenic substance or organism. "MA10 infection induced seven additional down-regulated (Hsp90aa1, Tcf7l2, Gnas, Sparcl1, Ywhag, Cpe, Sparc) and four upregulated DEGs (Ppp1r1b, Penk, Arpp21, Pcp4), whereas Aβ pathology resulted in five down-regulated (Cplx1, Syp, Meg3, Snhg11, Penk) and one upregulated DEG (Psen1)." (PMID 41497643, 2025).
SNHG11 also shares sentences with these, for which no sentence is quoted: glioma (3 papers); breast carcinoma (1); colorectal adenocarcinoma (1); Down syndrome (1); prostate adenocarcinoma (1); rectum adenocarcinoma (1); Sepsis (1).